TKT (transketolase)
Diseases named in the same sentence as TKT in open-access papers (continued):
Sharing a sentence is not in itself a finding about the gene and the disease.
hepatocellular carcinoma (17 papers, 2011 to 2025). A malignant tumor that arises from hepatocytes. "Wild-type TKT had high activity, whereas the ubiquitination-disrupting mutants (K319A and K16A) exhibited a complete loss of activity in both human and mouse hepatocellular carcinoma cells." (PMID 37653031, 2023). "In hepatocellular carcinoma, the nuclear translocation of transketolase promotes HDAC3 binding to the NR1H4 promoter, thereby inhibiting FXR expression." (PMID 40656893, 2025). "Although overexpression of TKT is one of the key factors in the malignant progression of hepatocellular carcinoma, its role in normal growth and development is equally crucial." (PMID 40230848, 2025). "Next, western blotting showed oroxylin A dose‐dependently decreased TKT protein levels after 48 h treatment in Hep1‐6 mouse hepatoma cells, whereas 14 days continuous treatment led to less TKT expression in HepG2 and SMMC‐7721 cells." (PMID 36314067, 2022). "As an essential enzyme in metabolism, TKT promotes hepatocellular carcinoma via metabolic mechanisms, nuclear localization, and the EGFR pathway." (PMID 35280908, 2022). "Noninvasive evaluation of the expression of angiopoietin-2 (Ang-2) and transketolase (TKT) in hepatocellular carcinoma (HCC) is of great significance for the clinical development of individualized treatment plans." (PMID 33520706, 2020). "In hepatocellular carcinoma (HCC), TKT knockdown causes R5P accumulation but inhibits cell proliferation, the explanation for this phenomenon is that the absence of TKT results in a decrease in NADPH, which disrupts the cell’s redox balance and causes an increase in ROS." (PMID 35110545, 2022). "Transketolase (TKT), a key rate‐limiting enzyme in the non‐oxidative branch of the pentose phosphate pathway (PPP), provides more than 85% of the ribose required for de novo nucleotide biosynthesis and promotes the development of hepatocellular carcinoma (HCC)." (PMID 36314067, 2022). "Finally, knockdown of transketolase (TKT) has been shown to result in a decrease in the levels of the antioxidant NADPH and an increase in ROS, and to remarkably reduce cell growth in two hepatocellular carcinoma cell lines and in vivo." (PMID 30108113, 2018).
glioma (14 papers, 2008 to 2025). A benign or malignant brain and spinal cord tumor that arises from glial cells (astrocytes, oligodendrocytes, ependymal cells). "CNTN1 was identified as a TAA along with other four TAAs (CRKII, CFL1, NME2, and TKT) in IDTH1-mutant lower grade gliomas through a proteomic and immunologic approach." (PMID 32752094, 2020). "Decreased expression of both G6PD and TKT was observed in glioma cells upon transfection with TERT dominant-negative construct or siRNA-mediated knock-down of TERT." (PMID 27148686, 2016). "This demonstrated that DNMT1, IDH3A, TACC3, and TKT could be incorporated as prognostic markers for glioma." (PMID 37875819, 2023). "Multidirectional changes in the activity of transketolase and hexokinase in the peritumoral zone of glial tumors were revealed in groups with a pronounced IDH1 mutation (significant increase) and with methylation of the MGMT gene promoter (significant decrease)." (PMID 35625744, 2022). "This indicated that a positive co-relation exists between hTERT and TKT in glioma cells." (PMID 27148686, 2016).
colorectal cancer (12 papers, 2018 to 2025). A primary or metastatic malignant neoplasm that affects the colon or rectum. "And in this study, we discovered that TKT expression was remarkably upregulated in colorectal cancer, abnormal high expression of TKT is associated with poor prognosis of colorectal cancer." (PMID 35110545, 2022). "In mouse xenograft models, colorectal cancer cells with enhanced SIRT5-transketolase signaling exhibited accelerated tumor growth." (PMID 41304967, 2025). "The interaction of mammalian TKT with glucose-regulated protein 78 (GRP78, also known as BIP) in colorectal cancer cells provides further support for the role of the malonylation-regulated, protein–protein interactions of TKT in the control of glucose fluxes." (PMID 38255994, 2024). "Because previous results indicated that TKT affected the malignancy of colorectal cancer, next, we wanted to explore the function of TKT in CRC." (PMID 35110545, 2022). "TKT was significantly overexpressed in samples of oxaliplatin-resistant colorectal cancer patients." (PMID 40227333, 2025). "Additionally, SIRT5 acts as a deacetylase, desuccinylase, and a demalonylase to activate target proteins such as lactate dehydrogenase B, and transketolase, promoting cell proliferation, oxidative stress, and cell survival in colorectal cancer." (PMID 41304967, 2025). "TKT is also upregulated in colorectal cancer cell lines, promoting proliferation and metastasis." (PMID 35624775, 2022). "In order to test whether TKT’s promotion of colorectal cancer metastasis is dependent on glycolysis, we used galactose which induced cells to survive on ATP provided by mitochondrial respiration instead of glucose." (PMID 35110545, 2022). "PPP-related enzymes, including transketolase (TKT) and G6PD, are overexpressed in several malignancies like breast, lung, ovarian, and colorectal cancer, wherein they are known to promote the development of chemoresistance." (PMID 37958470, 2023). "Transketolase (TKT), one of the PPP enzymes, is highly expressed in colorectal cancer, giving a poor prognosis." (PMID 35624775, 2022). "Further study demonstrated that TKT interacted with GRP78 and promoted colorectal cancer cell glycolysis through increasing AKT phosphorylation, thereby enhancing colorectal cancer cell metastasis." (PMID 35110545, 2022). "In colorectal cancer cells, blocking the sirtuin 5 expression does not affect the expression of TKT but decreases the TKT activity; the decrease is accompanied by impaired availability of ribose-5P for nucleotide synthesis and alleviated by overexpression of TKT in the sirtuin-5-silenced cells." (PMID 38255994, 2024). "We do not deny that TKT can work in the metastasis of colorectal cancer through the PPP, but our focus is whether TKT can regulate colorectal cancer metastasis in other ways besides PPP." (PMID 35110545, 2022). "Another study finds that SIRT5 activates the key enzyme transketolase (TKT) in the non-oxidized pentose phosphate pathway in a demalonylation-dependent manner, maintaining sufficient nucleotide levels for DNA synthesis and promoting colorectal cancer growth." (PMID 39979670, 2025).
pancreatic cancer (11 papers, 2013 to 2023). "It is suggested that S100A11 may regulate PPP in a TKTL1-TKT heterodimer-independent manner, which highlighting clinically a significant association between S100A11 and TKT in pancreatic cancer." (PMID 35752610, 2022). "G6PD and TKT were more highly expressed in pancreatic tumors from KPC mice than in pancreatic tissues from WT mice." (PMID 33664869, 2021). "HIF-1α target genes, TKT and CTPS1, regulating pyrimidine synthesis are associated with primary and metastatic pancreatic cancer tissues." (PMID 32707920, 2020). "An important metabolic role was recently ascribed to TKT to promote pancreatic cancer development through conversion of fructose to nucleotides for anabolic metabolism." (PMID 30214418, 2018). "This study revealed that inhibition of single metabolic enzyme transketolase by OT altered dynamics of cellular protein expression by interfering rates of de novo protein synthesis in MIA PaCa-2 pancreatic cancer cells." (PMID 23890079, 2013). "Thus, although fructose exposure resulted in enhanced expression of transketolase, culture for 14 days under fructose substitution conditions actually prolonged the cell doubling time of pancreatic cancer cells." (PMID 28032597, 2017). "It has also been reported that reduced expression of TKT and CTPS regulates flux into pyrimidine biosynthesis, which correlates with better prognosis in pancreatic cancer." (PMID 37242427, 2023). "In summary, we made the interesting observation that PRLR-SF signals induced via the NEK9-Hippo pathway reduce the expression of G6PD and TKT in the PPP and thereby reduce pancreatic tumor progression." (PMID 33664869, 2021). "Fructose was reported to induce transketolase flux to promote pancreatic cancer growth independent of glucose." (PMID 35681705, 2022). "TKT and CTPS1 co-localized with CAIX in PDAC tissue samples and in orthotopic pancreatic tumors." (PMID 32707920, 2020).
colon carcinoma (10 papers, 2006 to 2025). "It has been reported that Akt and TKT are correlated, and TKT can promote the phosphorylation of Akt, which in turn enhances the metastatic ability of colon cancer." (PMID 40227333, 2025). "Shin and co-workers described an upregulation of glycolytic enzymes including Transketolase in 5-FU resistant colon cancer cell lines, an argument for the potential involvement of TKTL1 in progression and therapy resistance." (PMID 21854597, 2011). "TKTL1 expression in colon cancer was shown to be upregulated as compared to TKT and TKTL2 expression using immunohistochemistry and cell culture assays." (PMID 21854597, 2011). "Furthermore, five of the seven glycolytic and PPP enzymes identified in our interactome analysis (GOT2, GPI, PGD, PSAT1, and TKT) were found to map to the “Metabolic reprogramming in colon cancer” pathway." (PMID 30108113, 2018). "G6PD and TKT enzymatic activities have been reported to be enhanced during late G1 and S cell cycle phases and specific upregulation of the oxidative branch has been demonstrated in colon cancer cells." (PMID 29290982, 2017). "Also, reserveratrol and oxythiamine (OT) were used to inhibit the activity of G6PDH and transketolase (TK), respectively, in colon cancer to induce apoptosis." (PMID 26437434, 2015). "We found that in colon carcinomas and urothelial carcinomas, expression of TKTL1 transketolase correlated with invasiveness of tumours and poor patient survival." (PMID 16465194, 2006). "Using these primers, a 79-fold overexpression of the TKTL1 gene was identified in one colon carcinoma tissue, whereas none of the tested colon carcinomas showed an overexpression of the TKT transcript." (PMID 16465194, 2006). "Western blot assays revealed that forced LINC01138 expression in colon cancer cells SW480 increased the expression of diacylglycerol kinase eta (DGKH) and Phosphodiesterase 4D (PDE4D), whereas resulted in decrease the expression of pyrroline‐5‐carboxylate reductase 1 (PYCR1) and transketolase (TKT)." (PMID 36366731, 2023).
cervical cancer (9 papers, 2009 to 2025). A primary or metastatic malignant neoplasm involving the cervix. "Additionally, MiR-497 improves the susceptibility of cervical cancer cells to cisplatin by inhibiting transketolase (TKT), lowering GSH levels, and increasing ROS production." (PMID 40403492, 2025). "A previous study reported that TKT phosphorylation affects its enzymatic activity in human cervical cancer cells." (PMID 36253417, 2022). "Such phenomenon is obvious in cervical cancer in which miRNA-497 shows low expression, while an increase occurs in expression profile of transketolase (TKT) (upregulation in 81.1% of samples)." (PMID 33921908, 2021). "In a word, TKTL1 plays an important role in total transketolase activity and proliferation of tumor cells in uterine cervix cancer." (PMID 19331662, 2009). "The real-time quantity PCR was used to determine the expression of transketolase gene family in uterine cervix cancer." (PMID 19331662, 2009). "The relative contributions of transketolase gene family to energy metabolism and proliferation of uterine cervix cancer cell have not been investigated." (PMID 19331662, 2009). "When human cervical cancer HeLa cells were synchronized to G1/S phase by double thymidine, endogenous levels of TKTL1, but not TKT and TKTL2, increased." (PMID 31175280, 2019).
lung carcinoma (9 papers, 2018 to 2025). "It showed that mRNA levels of TKT were up-regulated in breast, rectal, gastric and lung cancer patients." (PMID 35711845, 2022). "In conclusion, our study confirms previous findings that lung cancer patients with high TKT expression have a poor prognosis and highlight the importance of TKT as a potential therapeutic target." (PMID 35711845, 2022). "Furthermore, TKT is overexpressed in various cancers, including colorectal, pancreatic, breast and lung cancer, and patients with elevated TKT mRNA levels have decreased survival rates compared with those with lower levels." (PMID 40804482, 2025). "Expression of PPP enzymes such as G6P dehydrogenase (G6PD), 6-phosphogluconate dehydrogenase (PGD), and transketolase (TKT) was directly regulated by NRF2 in lung cancer cells, and NRF2 overexpression redirected cell metabolism to PPP-mediated purine nucleotide synthesis." (PMID 31078780, 2019). "To substantiate our results by 6-AN treatment in lung cancer cells, we checked the expression of PPP-related genes such as G6PD, HPGD, TKT, and TALDO1 in these cells 48 h after 6-AN treatment." (PMID 34827081, 2021). "In connection with this, the elevated expression of transketolase, an enzyme in the PPP, has been detected in lung cancer, confirming an increase in metabolic activity in this tumor type." (PMID 31370342, 2019). "These analyses demonstrated that mRNA expression of G6PD, glutaminase (GLS), hydroxy-prostaglandin dehydrogenase 15-(NAD) [HPGD], TKT, TALDO1, ribulose-5-phosphate-3-epimerase (RPE), and transketolase-like-1 (TKTL1) were more abundant in lung cancer patient samples." (PMID 34827081, 2021).
Obesity (9 papers, 2019 to 2025). Accumulation of substantial excess body fat. "Some of the hub genes identified were AURKA, MELK, and TKT for prenatal LOW vs HIGH nutrition, and CTSS and ITGB2 for late gestation malnutrition followed by early obesity development (LOW-HCHF and HIGH-HCHF vs NORM-CONV)." (PMID 33975549, 2021). "Additionally, NAC suppressed the expression of key obesity-related proteins, including fatty acid binding protein 4 (FABP4), monoamine oxidase A (MAOA), heat shock protein 70 (HSP70), aminoacylase-1 (ACY-1), and transketolase (TKT) in 3T3-L1 cells." (PMID 41149623, 2025). "The link between transketolase and obesity has not received much attention." (PMID 31258482, 2019).
ovarian carcinoma (9 papers, 2009 to 2025). A malignant neoplasm originating from the surface ovarian epithelium. "We validated the expression of proteins of interest (COL12A1, FUBP1, PLEC, SLC4A1, and TKT) using immunohistochemistry (IHC) and further characterized their expression in online ovarian cancer databases." (PMID 40565351, 2025). "TKT plays a key role in the pentose phosphate pathway and has been identified in ovarian cancer exosomes." (PMID 40565351, 2025). "We evaluated the usefulness of YAP, TEAD4, SMAD2, SMAD3, H2A.X, ALD1A1, CD71, TKT and TKTL1 as diagnostic or prognostic markers in patients with ovarian cancer." (PMID 34205023, 2021). "Our list of peptides found in ovarian cancer specimens includes fragments derived from the proteins vitronectin, transketolase and haptoglobin." (PMID 24694173, 2014). "We evaluated the differences in the expression of the YAP, TEAD4, SMAD2, SMAD3, H2A.X, ALD1A1, CD71, TKT, and TKTL1 in ovarian cancers and benign cysts." (PMID 34205023, 2021). "The H2A.X, CD71, SMAD3 and 4, TKT, and TKTL1 proteins require further studies to confirm their suitability for clinical use in ovarian cancer patients." (PMID 34205023, 2021). "Moreover, TKT expression was found to be negatively correlated with TMB in CHOL, ovarian cancer, and THCA, but positively correlated in KICH, KIRC, LIHC, PRAD, STAD, and UCEC." (PMID 40230848, 2025).
glioblastoma (8 papers, 2013 to 2025). The most malignant astrocytic tumor (WHO grade IV). "A prior investigation had indicated an upregulation of TKT mRNA expression in radioresistant glioblastoma cells." (PMID 38216672, 2024). "A previous study highlighted the upregulation of TKT mRNA in radioresistant glioblastoma cells." (PMID 38216672, 2024). "Importantly, glioblastoma multiforme (GBM) patient tumors bearing TERT promoter mutations (C228T and C250T) known to be associated with increased telomerase activity; exhibited elevated Nrf2 and TKT expression and decreased glycogen accumulation." (PMID 27148686, 2016).
diabetes (7 papers, 2012 to 2024). "Taken together, these studies strongly implicate perturbed TKT function in the development of diabetes and various cancers." (PMID 30646877, 2019). "TKT is the best studied transketolase, and previous studies reported an altered activity in patients suffering from diabetes and various cancers." (PMID 30646877, 2019). "Genetic variation in the transketolase gene was investigated in a study involving 240 subjects with diabetes (including type 1, latent autoimmune diabetes in adults (LADA), and type 2 diabetes), with or without diabetic nephropathy, including end-stage renal disease (ESRD) in some cases." (PMID 38928135, 2024). "Transketolase is a rate-limiting enzyme of pathways proposed to confer hypothetical protection against hyperglycemia, with neuropathic symptoms and reduced thermal sensation in recently diagnosed diabetes." (PMID 38928135, 2024). "Given the potential role of TKT in SARS-CoV-2 replication identified here, elevated TKT levels may be one of the factors that predispose diabetes patients to experience severe COVID-19." (PMID 34677415, 2021). "Therefore, a lack of adaptive increase of thiamine transmembrane transport allowing a further protective increase of transketolase activity might contribute to compromised protective mechanisms in diabetes and CKD and to the development of glycotoxic injury." (PMID 29783710, 2018). "The activation of transketolase plays a crucial role in oxidative and non-oxidative pentosephosphate pathways that inhibit vascular complications of diabetes." (PMID 22792314, 2012). "Although we have shown increased transketolase activity and intracellular thiamine diphosphate levels in CKD patients (either with or without diabetes) the expression of thiamine transporters was either decreased or unchanged." (PMID 29783710, 2018).